IL10 (interleukin 10)
Diseases named in the same sentence as IL10 in open-access papers (continued):
Sharing a sentence is not in itself a finding about the gene and the disease.
COVID-19 (continued). "Conversely, significantly higher levels of GM-CSF, IFN-β, IL-10, and IL-2 and low levels of Eotaxin, IL-4, IL-5, MCP-1, and MIP-1β, were distinctive to Non-SOT COVID-19 patients relative to HCs, but not in SOTRs." (PMID 35075453, 2022). "Compared with mild and survivor COVID-19 cases, severe and non-survivor cases had lower counts of CD4/CD8 T-cells and higher levels of IL-10." (PMID 35572964, 2022). "For instance, patients with COVID-19 who were admitted in the intensive care unit (ICU) showed a higher abundance of main proinflammatory cytokines, such as TNFα, IL-2, IL-7, IL-10, MCP1, MIP1A, G-CSF, and IP10 in comparison with non-ICU patients." (PMID 35342407, 2022). "Severe COVID-19 sufferers demonstrated increased levels of non-classical monocytes, several plasma chemokines such as CXCL9 cytokines (IL-6 and IL-10), and ROS as opposed to mild COVID-19." (PMID 36016187, 2022). "In contrast, the serum levels of IL-4, IL-6, IL-10, interferon-γ, and TNF-α were lowest in infected HD patients compared to non-infected HD patients or COVID-19-infected patients with normal renal function." (PMID 33466527, 2021). "Proinflammatory molecules, such as IL-2, IL-4, IL-5, IL-6, IL-10, IL-13, TNF-α, IFN-Υ, and CRP, were found at higher levels in COVID-19 patients with DM than in COVID-19 patients without DM." (PMID 34786431, 2021). "We found that the serum levels of multiple pro-inflammatory cytokines or biomarkers, including IL-6, IL-10, IL-8, TNF-α, IL-1β, IL-2R, ferritin, hs-CRP and procalcitonin were substantially elevated in non-survivors with COVID-19." (PMID 34521370, 2021). "Interestingly, the secretion of IL-6, IL-8, TNF-α, IFN-γ and IL-10 was significantly elevated in CARγ and CARζ cells treated with SARS-CoV-2 virions, suggesting that these CAR macrophages may not be suitable for application in severe patients or patients with late-stage COVID-19." (PMID 34367135, 2021). "Furthermore, in the case of COVID-19, the production of counterbalancing anti-inflammatory cytokines, specifically IL-10, may not function to limit the cytokine storm as previously thought, but rather enhance the pro-inflammatory environment in which a cytokine storm can develop." (PMID 34251989, 2021). "Other authors pointed out that the sum of IL-10 and TNF-α levels allowed to distinguish MISC from severe COVID-19 presentations, but not between severe and mild MIS-C." (PMID 34778310, 2021). "Unlike increased levels of TNFα, IL-6, IL-8, IL-10, CXCL8, and IP-10 observed in H1N1 infected pregnant patients, COVID-19 pregnant patients showed relatively lower expressions of pro-inflammatory and anti-inflammatory cytokines." (PMID 34012458, 2021). "The fact that high levels of anthranilic acid predict the maintenance of high levels of IL10 and IL18 suggests (but does not prove) that the kynurenine pathway has an immunomodulatory impact on COVID-19 pathogenesis." (PMID 33707411, 2021). "Different from recent studies showing remarkably elevated levels of IL-6, IL-10, and IFN-γ in severe COVID-19 patients, we only observed notably increased levels of IL-6 in severe patients." (PMID 33390771, 2021). "COVID-19 positive patients had lower PON1 activities and galectin-3 concentrations, and higher PON1, CRP, IL-10, and ACE2 concentrations than COVID-19 negative patients." (PMID 34205807, 2021). "Healthy pregnant women showed high levels of interleukins including IL-2, IL-5, IL-10, and IL-12, as well as high levels of growth factors such as b-NGF and VEGF, which were largely decreased in COVID-19 pregnant and non-pregnant patients." (PMID 34012458, 2021). "Previous results from our group have shown that circulating IL-6 and IL-10 were lower, while TNF-α and IL-8 levels were higher, in the same critically ill COVID-19 patients compared to the critically ill non-COVID-19 patients." (PMID 34575667, 2021).
COVID-19 (continued). "IL-10-producing Tr1 cells and suppressor CD8+T cells were also increased in severe COVID-19 patients, whereas TGF-β-producing Th3, but not CD8+ T cells, were increased in both mild and severe patients." (PMID 33692788, 2021). "SARS and COVID-19 do not lead to the upgrade of TNF-α, but the increase of IL-6 and IL-10 is more prevalent in COVID-19." (PMID 32754163, 2020). "Meanwhile, serum concentrations of IP-10, MCP-1, sTREM-1, IL-10, and the neutrophil-to-lymphocyte ratio (NLR) in peripheral blood could distinguish between COVID-19 survivors and non-survivors and were significantly associated with mortality." (PMID 39654886, 2024). "However, the combined detection of IP-10, MCP-1, sTREM-1, IL-10, and NLR did not improve the predictive value for COVID-19 mortality outcome." (PMID 39654886, 2024). "Similarly, the plasma level of IL-2, IL-7, IL-10, and TNF-α increased in ICU COVID-19 patients compared to non-ICU COVID-19 patients." (PMID 38152668, 2023). "One of the first studies to evaluate the serum cytokine storm in COVID-19 patients showed that several pro-inflammatory mediator levels, such as TNFα, IL-2, IL-7, IL-10, G-CSF, CXCL10, CCL2 and CCL3, were increased in ICU (n = 13) compared to non-ICU COVID-19 patients (n = 28)." (PMID 36941580, 2023). "Also, patients with COVID-19 were characterized by increased secretion of proinflammatory cytokines CCL20/MIP3ɑ, IL-10, IL-15, IL-27 in non-survivors than in controls." (PMID 36758022, 2023). "The production of cytokines in COVID-19 patients and CD4+ T lymphocytes isolated from SARS-CoV-2-vaccinated subjects stimulated with a peptide pool predominantly expressed IL-2 and IFN-γ, whereas IL-17A, IL-4, and IL-10 were less frequent and not significant." (PMID 38140191, 2023). "Thus, we were the first to show that MSC transplantation in severe COVID-19 patients led to the elevation of plasma levels of pro-inflammatory cytokines such as IP-10, MIP-1α, G-CSF, and IL-10 without disease aggravation." (PMID 36901868, 2023). "Similarly, Eotaxin (p=0.080), IL-10 (p=0.095), IL-18 (p=0.095) and IL-2Ra (p=0.071) were higher and IFN-β (p=0.094) was lower in Non-SOT COVID-19 patients (FDR<0.26 for all)." (PMID 35075453, 2022). "Furthermore, IL-2, IL-7, IL-10, G-CSF, IP-10, MIP-1α and1β, and TNF-α were higher in ICU COVID-19 patients than non-ICU patients." (PMID 35401519, 2022). "In a different way, whereas IFN-α showed a positive correlation with IL-6 in the control group without SIgA, the IFN-α showed a positive correlation with IL-10 in the control group with SIgA, with IFN-γ in the COVID-19 group with SIgA, and with IL-13 in both COVID-19 groups." (PMID 35686128, 2022). "Regardless of the unchanged values of BDNF in different phases of COVID-19, we found a positive correlation between BDNF and MMP-9, MMP-8, and VEGF A, as well as a strong negative correlation of BDNF with IL-10 and cytokines ratios IL-10/IL-1, IL-10/IL-6, IL-10/IL-17, and IL-10/TNF-α." (PMID 36438922, 2022). "In addition to IL-6, the serum levels of IL-2R, IL-10, IL-1β, IL-4, IL-8, IL-17 and TNF-α were also elevated in both severe and non-surviving COVID-19 patients." (PMID 35237162, 2022). "Furthermore, prognostic biochemical markers in COVID-19 including the inflammatory cytokines C-reactive protein (CRP), interleukin-6, and interleukin-10, were not measured due to limited resources." (PMID 33781275, 2021). "Moreover, serum levels of IL-6, IL-8, IL-10 and CRP were higher in severe COVID-19 patients compared to non-severe patients." (PMID 34603318, 2021). "While the absence of an IL-10 response in SARS is thought to contribute to early deterioration, we suspect IL-10 to protect the lung from early immune-mediated damage and to interfere with viral clearance in COVID-19." (PMID 33746948, 2021).
COVID-19 (continued). "COVID-19 patients suffered from headache had significantly higher serum levels of HMGB1, NLRP3, ACE2, and IL-6 than COVID-19 patients without headache, whereas CGRP and IL-10 levels were similar in the groups." (PMID 34384355, 2021). "Compared to nondiabetic COVID-19 patients, diabetic COVID-19 patients are characterized by a higher percentage of CD4+ T cell and a lower percentage of CD8+ T cells and higher serum levels of IL-6, IL-2, IL-10, and INFγ." (PMID 34157054, 2021). "COVID-19 patients with headache had significantly higher serum levels of HMGB1, NLRP3, ACE2, and IL-6 than COVID-19 patients without headache, whereas CGRP and IL-10 levels were similar." (PMID 34794375, 2021). "This phenomenon suggested the decrease of T-cells in COVID-19 patients may be due to the negative effects of high serum concentrations of TNF-α, IL-6, IL-10 on the survival or proliferation of T-cells." (PMID 33435865, 2021). "Serum inflammatory factor levels of IL-2, IL-1β, IL-5, IL-4, IL-6, IL-8, IL-10, IL-17, IL-12P70, IFN-α, TNF-α, IFN-γ, endotoxin, CRP, and hs-CRP of non-severe COVID-19 patients across different age groups (< 50, 50–60, 60–70, and ≥ 70 years) were not significantly different." (PMID 33065551, 2020). "Similarly, in severe COVID-19 cases, ICU patients had higher plasma levels of IL-2, IL-7, IL-10, GSCF, MCP1, MIP1A, and TNFα compared to non-ICU patients." (PMID 32754890, 2020). "Levels of serum IL-10 (p = 0.0001), IL-6 (p = 0.002), MIP-3α (p = 0.02) and CD40-L levels (p = 0.002) significantly increased from 5 to 9 day of illness to 10–21 day of illness in patients with moderate-to-severe COVID-19, but not in those with mild illness." (PMID 33199778, 2020). "IL-10 was strongly elevated in COVID-19 pneumonia versus healthy controls (SMD = 1.26, 95% CI 0.96–1.57, p < 0.00001), but the comparison between COVID-19 with pneumonia and COVID-19 without pneumonia groups was not significant (SMD = 0.15, 95% CI –0.24–0.54, p = 0.45)." (PMID 41585373, 2025). "Studies have found that IL-10 increases ACE2 mRNA expression in lung-derived Calu-3 cells and human umbilical vein endothelial cells (HUVEC), thereby providing cardiopulmonary protection in COVID-19 using a negative feedback mechanism that inhibits inflammation." (PMID 36329841, 2022). "In addition, we found that calcium levels are reduced in severe COVID-19 patients, and this parameter showed strong negative correlations with MCP-1, IL-18, IL-8, IL-6, and IL-10 and positive correlation with T cell number, indicating its good prognostic factor." (PMID 33692788, 2021). "In addition, comparing the significant correlations observed in the mild COVID-19 groups, we highlighted above that the lack of correlations between IL-10 and IFN-β could favor the mucosal immune response in the mild A COVID-19 subgroup." (PMID 33717074, 2021). "A previous study found that intensive care unit (ICU) patients with COVID-19 had higher plasma levels of interleukin (IL)-10, IL-2, IL-7, tumor necrosis factor (TNF)-α, IP-10, monocyte chemoattractant protein 1, Macrophage inflammatory protein 1A than those in non-ICU patients with COVID-19." (PMID 32727465, 2020). "Clinical evaluation of 41 COVID-19 patients (Non-ICU: 28 and ICU: 13) for over 26 chemokines and cytokines revealed increased levels of 16 of them such as IL-1β, IL-1RA, IL-17, IL-8, IL-9, IL-10, basic FGF, G-CSF, GM-CSF, IFN-γ, CXCL10, CCL2, CCL3, CCL4, PDGF, TNF-α." (PMID 33335518, 2020).
COVID-19 (continued). "Furthermore, distinct from cellular immunity in European and Asian COVID-19 convalescents, we observed strong T cell immunogenicity against viral accessory proteins (ORF3a, ORF8) but not structural proteins, as well as a higher IL-10/IFN-γ cytokine ratio profile." (PMID 37219944, 2023). "Additionally, based on a meta-analysis included about 23 studies, IL-6, IL-8, IL-10, IL-2R, and TNF-α cytokine levels were significantly higher and T-lymphocyte levels were significantly lower among serum of severe cases as compared to non-severe COVID-19 patients." (PMID 35223745, 2022).
Sepsis (1,173 papers, 2005 to 2026). Sepsis is defined as life-threatening organ dysfunction caused by a dysregulated host response to infection. "Studies have investigated the IL10-1082G/A polymorphism concerning the susceptibility to sepsis in the Asian population and Afro-Colombian patients." (PMID 41598258, 2026). "A meta-analysis of 11 studies on the adult population concluded that the IL10-1082G/A polymorphism is significantly associated with susceptibility to sepsis in Asian populations." (PMID 41598258, 2026). "Our results suggest the role of IL10-1082G/A polymorphism as a possible predictive risk factor for early neonate sepsis." (PMID 41598258, 2026). "Based on our observations, the genotypic testing models revealed that in the codominant model, the IL10-1082G/A polymorphism increased the odds of early-onset sepsis in premature neonates." (PMID 41598258, 2026). "IL-10 is a central anti-inflammatory and immunosuppressive cytokine, exerting a dual role in sepsis: it limits tissue injury caused by excessive inflammation while simultaneously promoting immunoparalysis during later stages of the disease." (PMID 41300951, 2025). "IL-10 also showed elevated diagnostic utility with 82.2% positivity in sepsis cases, though its comparative statistics were less emphasized." (PMID 40647525, 2025). "IL-10 consistently demonstrates high diagnostic performance for bacterial infection and sepsis detection in febrile neutropenic patients." (PMID 40647525, 2025). "Low interleukin-6 (IL-6) and high interleukin-10 (IL-10) levels are associated with improved outcomes in sepsis." (PMID 41158471, 2025). "A compensatory increase in IL-10, an anti-inflammatory cytokine, is known to correlate with severity of the inflammatory response and associated organ failure in severe sepsis." (PMID 40691621, 2025). "While previous studies demonstrated that both elevated IL-10 and lymphopenia are independently associated with sepsis mortality, their combination appears to provide enhanced predictive value." (PMID 41001389, 2025). "An excess of IL-10 induces immunoparalysis, exposing the individual carrying the G allele to secondary infections, resulting in sepsis and mortality with impaired bacterial clearance." (PMID 41013722, 2025). "The IL-10 rs1800896 polymorphism was associated with an increased incidence of complications, particularly respiratory failure and sepsis." (PMID 40692949, 2025). "Elevated IL-10 has been linked to T-cell exhaustion and impaired immune surveillance in sepsis and advanced atherosclerosis." (PMID 41419927, 2025). "During the immune suppression stage of sepsis, M2 macrophage polarization contributes to immune tolerance and increases susceptibility to secondary infections through mechanisms such as IL-10 release and reduced HLA-DR expression." (PMID 39910395, 2025). "Clinically, elevated plasma IL-10 levels demonstrate strong correlations with increased nosocomial infections and mortality rates, validating its central role in sepsis-associated immunosuppression." (PMID 40364841, 2025). "IL-10, an anti-inflammatory cytokine secreted by M2 macrophages, is inversely correlated with prognosis in sepsis—higher levels of IL-10 are linked to worse outcomes." (PMID 39910395, 2025). "We have previouslyreported that MDSC expansion and sepsis-induced immunosuppression are inhibited inS100A9-deficient mice; for example, these mice havesignificantly lower levels of IL-10." (PMID 40458301, 2025). "In brief, genetically predicted IL-10 dropped a 32% (OR, 0.68; 95% CI =0.52-0.90, P = 0.006) risk of sepsis in the IVW method." (PMID 38504987, 2024). "The key role of increasing levels of IL-10 in the anti-inflammatory response causes worse outcomes in oncologic neutropenic patients with sepsis." (PMID 38254697, 2024).
Sepsis (continued). "For example, increases in IL-6 and IFN-γ levels are associated with sepsis and wound disruption, while the IL-10 concentration can be used to determine the occurrence of postoperative complications such as atrial fibrillation." (PMID 38704573, 2024). "Domestic scholars have found that a single nucleotide polymorphism in the IL-10-1082 gene is closely related to the tendency to develop sepsis." (PMID 38848433, 2024). "This study aims to study the diagnostic significance of conventional and new markers, interleukin-10 (IL-10), in predicting the severity of sepsis." (PMID 39507174, 2024). "MR insights intimated that reduced genetically-predicted interleukin-10 (IL-10) levels causally correlated with a heightened sepsis risk (odds ratio [OR] 0.68, 95% confidence interval [CI] 0.52-0.90, P=0.006)." (PMID 38504987, 2024). "An adenine (A) mutation to guanine(G) at site 1082 of the IL-10 promoter region reduces the content of intracellular IL-10, thus further affecting the occurrence and development of sepsis." (PMID 38848433, 2024). "A study examining how NAC treatment affects changes induced by sepsis in conscious rats revealed a reduction in inflammatory biomarkers (IL-6, tumor necrosis factor-α (TNF-α), and IL-10) linked to sepsis." (PMID 39064168, 2024). "Investigations into this possibility, however, have been unable to demonstrate an association between high levels of IL-10 and increased risk of sepsis, suggesting that IL-10 impacts additional processes critical for recovery from ALF." (PMID 38094302, 2023). "Some cytokines associated with inflammation, such as IL‐1β, TNF‐α, and IL‐10, have been found to play essential roles in the occurrence and development of sepsis." (PMID 37382273, 2023). "Remarkably, the six sepsis-elevated genes in the lungs (Il10, Tnf, Ccl3, Ccl4, Ccl12, and Nos1) were more susceptible to the nuclear blockade with the NTCI than their homologs in the kidneys." (PMID 37638006, 2023). "Through correlation analysis, Interleukin-10 (IL-10) was identified as an inflammatory cytokine associated with both IE and sepsis." (PMID 38332910, 2023). "C. dubliniensis immunized Il10-deficient mice had a significantly higher mortality following sepsis challenge compared to immunized wild-type (WT) mice (P = 0.0136) and nonimmunized II10-deficient mice (P = 0.025)." (PMID 37681975, 2023). "ITK inhibitor-treated mice with sepsis show attenuated IL-17A signaling, which is associated with the upregulation of IL-10/Nrf2 signaling and the amelioration of depression-like symptoms in mice." (PMID 37175808, 2023). "It is important to note that Il10-deficient mice lack IL-10 during both immunization and the lethal sepsis challenge." (PMID 37681975, 2023). "Elevated ratios of anti-inflammatory to pro-inflammatory cytokines (e.g. IL10/TNF) are proposed markers of sepsis-induced immunosuppression, and are associated with multiple organ failure and increasing sepsis severity and mortality." (PMID 37033939, 2023). "Another study found that polymorphisms in genes resulting in high TNF‐α and low IL‐10 production were associated with higher rates of sepsis in patients with AH." (PMID 37125245, 2023). "DCs are susceptible to sepsis-induced apoptosis, with reduced HLA-DR expression, elevated IL-10 secretion, and induction of T cell anergy or Treg cell proliferation." (PMID 37434129, 2023). "As a potent endogenous immunosuppressive cytokine, IL10 is considered as the most important factor associated with rapid death in patients with sepsis." (PMID 38259686, 2023). "Strikingly, we observed almost identical survival between our Il10-deficient mice and IL-10 depletion experiments, highlighting the role of this cytokine during lethal sepsis." (PMID 37681975, 2023). "The gene encoding Interleukin 10 (IL10) was robustly responding to sepsis in the lungs being reduced almost 20-fold by NTCI albeit the almost 70-fold lower expression in the kidneys was unchanged by NTCI." (PMID 37638006, 2023).